NFE2L2 (NFE2 like bZIP transcription factor 2)
Diseases named in the same sentence as NFE2L2 in open-access papers (continued):
Sharing a sentence is not in itself a finding about the gene and the disease.
cancer (continued). "Nuclear factor erythroid 2-related factor 2 (Nrf2 or NFE2L2), an antioxidant transcription factor, plays a pivotal role in regulating ferroptosis in cancer cells." (PMID 40191433, 2025). "Pathway analysis highlighted the enrichment of several terms, and beyond general ones like infection‐ and cancer‐related molecular cascades, we specifically observed the enrichment of “Nuclear events mediated by NFE2L2” and “KEAP1‐NFE2L2 pathway”." (PMID 40501038, 2025). "The oncogene MYCN and the cancer-related gene NFE2L2 are located on chromosome 2 at 2p24.3 and 2q31.2, respectively." (PMID 40670349, 2025). "Of the currently 487 LUSC samples in TCGA (Pan-cancer Atlas), 21% have PTEN mutations (around 100 patients); but only 10 samples exhibit PTEN and NFE2L2 mutations and only 8 show PTEN and KEAP1 co-existing mutations." (PMID 40676628, 2025). "The NFE2L2 pathway, often upregulated in cancers, regulates antioxidant response and ferroptosis resistance." (PMID 39935430, 2025). "NFE2L2 encodes NRF2, a transcription factor that upregulates antioxidant and detoxification genes, promoting cancer cell survival under oxidative stress." (PMID 40926327, 2025). "In summary, the TFs identified in this study were determined to be key molecules regulating cancer progression through NFE2L2." (PMID 40649369, 2025). "DNA methylation of KEAP1 has been more frequently studied than NFE2L2 across multiple cancer models, revealing distinct methylation patterns at KEAP1 promoter region when comparing normal and tumor lung tissues." (PMID 40563292, 2025). "According to a recent pan-cancer whole genome analysis, non-small cell lung cancer has the highest mutation frequency in both KEAP1 and NFE2L2 (ICGC/TCGA Pan-Cancer Analysis of Whole Genomes Consortium, 2020)." (PMID 40394395, 2025). "In advanced cancers, persistent NRF2 activation—through KEAP1/NFE2L2 mutations or oxidative adaptation—drives epithelial-to-mesenchymal transition, metabolic reprogramming, and immune evasion, promoting tumor invasion (T) and metastasis (M)." (PMID 41470226, 2025). "The modulation of NFE2L2 by transcription factors plays a significant role in metabolic reprogramming and the malignant progression of cancer." (PMID 39664581, 2024). "In contrast, the KEAP1/NFE2L2 pathway is involved in managing cellular stress and can shield cancer cells from the impact of radiation therapy." (PMID 38741207, 2024). "In contrast to Zhao’s findings, in these tumor entities the hypermethylation on the NFE2L2 promoter suppresses its transcription and leads to a subsequent inhibition of cancer progression." (PMID 38666930, 2024). "This review outlines the current knowledge on the link between NFE2L2 and ferroptosis - a form of regulated cell death characterized by iron-dependent lipid peroxidation - within cancer cells." (PMID 39534872, 2024). "Combined with 19 genes related to cuproptosis in the current cancer database, NFE2L2, PDHA1, PDHB, DLD, and GLS showed significant differences between the two groups." (PMID 38200445, 2024). "While NFE2L2 activation can protect normal cells from oxidative damage, its overexpression in cancer cells contributes to drug resistance by upregulating antioxidant defenses and inhibiting ferroptosis." (PMID 39534872, 2024). "In cancer cells, The NFE2L2 expression is regulated not only vai Keap1-mediated degradation of protein, but also via oncogenic signaling pathways like KRAS-BRAF-MYC." (PMID 39877159, 2024).
cancer (continued). "This review will first provide an overview of the molecular pathways involved in ferroptosis, followed by an in-depth discussion of how NFE2L2 is activated and contributes to drug resistance during ferroptosis-mediated cancer therapy." (PMID 39534872, 2024). "This occurs through the prevention of BTRC-mediated degradation of NFE2L2, which in turn sustains high levels of SLC7A11, thereby reducing the susceptibility of cancer cells to ferroptosis." (PMID 39534872, 2024). "This defense mechanism provides cancer cells with a survival advantage, especially in oxidative and stress-inducing environments, highlighting the therapeutic potential of targeting NFE2L2." (PMID 39534872, 2024). "NFE2L2 plays a protective role in a wide range of human diseases, including cancer, neurodegenerative disorders, cardiovascular diseases, metabolic syndromes, chronic inflammatory conditions, liver and renal diseases, and infections." (PMID 39534872, 2024). "NFE2L2 is a key regulator of antioxidant response elements to mitigate ROS levels in cancer cells and has been reported to be modulated by NO." (PMID 39352757, 2024). "The upregulation of G6PD through NFE2L2 activation not only aids in the detoxification of ROS but also contributes to the resistance of cancer cells to ferroptosis." (PMID 39534872, 2024). "Among the 20 significantly derepressed pathways mediated by NFE2L2, 12 directly involve cancer pathways." (PMID 39169204, 2024). "HSF1 can also be up-regulated at the transcriptional level by NFE2L2 during oxidative stress, which is relatively higher in cancer cells." (PMID 37894333, 2023). "NFE2L2 is a transcription factor that shapes the antioxidant response in driving cancer progression, metastasis, and resistance to therapy." (PMID 38138427, 2023). "Sulforaphane is a common antioxidant that has been found to affect NFE2L2 and to regulate phase II enzymes, and its potential therapeutic effects on cancer have led to a great deal of research interest." (PMID 37298157, 2023). "In accordance with prior studies, our findings also indicate a correlation between NFE2L2 MU and Nrf2-activating MU and unfavorable prognosis in our two comprehensive cancer datasets." (PMID 37794491, 2023). "Previous evidence showed that NFE2L2 expression is indicative of poor prognosis in many cancer types." (PMID 37373496, 2023). "Meanwhile, a study shows that Chinese cancer patients, particularly NSCLC patients, with NFE2L2 mutation, can benefit more from ICIs treatment than other treatments including chemo- and radiotherapies." (PMID 37794491, 2023). "In cancer, NFE2L2 promotes aggressive tumorigenesis and confers therapeutic resistance via metabolic reprogramming and increased antioxidant capacity." (PMID 37985752, 2023). "CAT and GSTP1 genetic variability was thoroughly studied in oxidative-stress-related diseases, especially different types of cancer, while in neurodegeneration, NFE2L2 and KEAP1 have recently gained the interest of researchers." (PMID 36829875, 2023). "We used the MSK MetTropism cohort to evaluate the molecular characteristics of NFE2L2 MU across pan-cancers, and found that 1.9% of patients (n = 487) had at least one NFE2L2 MU." (PMID 37794491, 2023). "For example, SLIdR identified NFE2L2 as the SL partner of the mutated KEAP1, both of which play an important role in cancer through Nrf2 pathway activation." (PMID 36517508, 2022). "Experimental–computational analysis revealed that the Nrf2(NFE2L2)-EMT-Notch1 network coordinates cancer cells in the migrating front during collective migration." (PMID 36231068, 2022). "Clinical trials have shown that TAK-228 is most effective in treating cancers with constitutive activation of the NRF2 coding gene NFE2L2." (PMID 35484114, 2022). "NFE2L2 (also known as NRF2) responds to oxidative stress to help prevent cancerous transformation of normal cells but is often up-regulated in established cancers and, thus, can be described as a double-edged sword." (PMID 36035174, 2022).
cancer (continued). "We demonstrate that APOBEC effectively deaminates NFE2L2 at the locations that confer high cancer effect." (PMID 35872531, 2022). "Among them, the family member that is widely investigated is NFE2L2, which has been confirmed as a driver gene of malignant tumor." (PMID 35664314, 2022). "On the other hand, NFE2L2 silencing increases the sensitivity of cancer cells to chemotherapeutic drugs." (PMID 35056649, 2022). "Unfortunately, NFE2L2 activation triggers antioxidant pathways that protect cancer cells against the effects of chemotherapeutic agents." (PMID 35056649, 2022). "At the transcriptional level, SLC7A11 is upregulated in cancer cells by transcription factors, such as nuclear factor erythroid 2-like 2 (NFE2L2/NRF2) and activating transcription factor 4 (ATF4)." (PMID 34742351, 2021). "Most of the inactivating mutations in the NFE2L2 gene were detected within ETGE and DLG motifs in various cancers such as lung, head, neck, and esophageal carcinoma." (PMID 33808001, 2021). "But until now little success has been achieved in developing safe and effective KEAP1/NFE2L2 inhibitors for cancer therapy." (PMID 34381706, 2021). "Knock down of NFE2L2 in human cancer cells was effective in altering the NFE2L2/NRF2 pathway and improving chemosensitivity." (PMID 34414229, 2021). "Intact autocrine EGFR signaling cascade, induced by the redox master regulator Nuclear factor erythroid-derived 2-like 2 (Nrf2/Nfe2l2) through Akt, is an important adaptive survival response that contributes to drug resistance in Kras mutant cancer cells." (PMID 34453639, 2021). "CRSO identified NFE2L2 as con‐GCRs in 4 cancer types as part of 4 distinct rules that had comparatively low coverage and single‐rule performance." (PMID 33769711, 2021). "Direct comparison of FPKM distributions show us that all three transcription factors: BACH2, MAFK and NFE2L2 are downregulated in cancer cells." (PMID 33806327, 2021). "Recent studies have reported that KEAP1/NFE2L2/CUL3 mutated in many cancers and led to worse survival outcomes in many cancers, our survival analysis also confirmed this." (PMID 34617407, 2021). "The role of NFE2L2 in cancer is still a matter of debate, since it has been reported to act pro- and anti-tumorigenic." (PMID 34458153, 2021). "Nuclear factor-erythroid 2-related factor 2 (Nrf2, also called NFE2L2) is one of the transcription factors involved in cancer cell survival pathways and implicated in protecting cancer cells from apoptosis." (PMID 33414469, 2021). "Our findings revealed the possible role of NFE2L2 across cancers, suggesting that NFE2L2 is a potential prognostic biomarker and is correlated with immune infiltration in many cancers, especially in LGG." (PMID 33101586, 2020). "The miR-101 binds to the 3′UTR region of NFE2L2, thus influencing its expression, promoting the suppression of cell proliferation and enhancing the sensitivity of cancer cells to ROS." (PMID 33287295, 2020). "The basic leucine zipper transcription factor NRF2 (gene name: NFE2L2) is emerging as a major regulator of cellular metabolism in both normal and cancer cells." (PMID 33080927, 2020). "Comparative analysis of methylation sites associated with genes within the KEAP-NRF2 and PI3K pathway in this study suggested the MAF transcription factor and NFE2L2 (NRF2) are hypermethylated in the four TCGA cancers screened." (PMID 33143142, 2020). "Our study is aimed at analyzing the prognostic value of NFE2L2 in pan-cancer and at revealing the relationship between NFE2L2 expression and tumor immunity." (PMID 33101586, 2020). "Results showed NFE2L2 expression impacted patients' DSS in 6 cancer types (ACC, KIRC, LGG, PAAD, SARC, and UCS)." (PMID 33101586, 2020).
cancer (continued). "Five TFs, SUZ12, SMAD4, REST, EZH2 and NFE2L2, were found to be enriched in all four cancers, suggesting that transcriptional dysregulation of tumors with aberrant AMPK signaling involved direct physical associations of these TFs with target DEGs." (PMID 32807122, 2020). "Due to the small number of normal tissue samples in TCGA database, we further integrated the normal tissue data from the GTEx database and the tumor tissue data from TCGA database to analyze the differences in NFE2L2 expression in 27 cancer types." (PMID 33101586, 2020). "In this study, we found for the first time that abnormal expression of NFE2L2 exists in human pan-cancer including ACC, LGG, and PAAD." (PMID 33101586, 2020). "Next, we investigated the relationship between NFE2L2 expression and the prognosis of patients in pan-cancer." (PMID 33101586, 2020). "Nrf2, also known as Nfe2l2, is of particular interest as its role in cancer development is conflictual." (PMID 32824383, 2020). "While the activation of NFE2L2 has been evaluated in cancer prevention in clinical trials, it has been claimed that the constitutive activation of NFE2L2 contributes to the survival and growth of cancer cells in many types of tumours." (PMID 31752195, 2019). "NFE2L2 has been shown to support the progression of several types of cancers and to promote their resistance to chemo- and radiotherapy." (PMID 31752195, 2019). "Silencing of NFE2L2 induced a higher mRNA expression of ESR1 in the NFE2L2 downregulated cancer cell lines OVCAR3 (p = 0.003) and ES2 (p < 0.001), confirming genetic interactions of NRF2 and ERα." (PMID 30597961, 2018). "NFE2L2 silencing showed a higher expression of ESR1 in the NFE2L2-downregulated cancer cell lines OVCAR3 (p = 0.003) and ES2 (p < 0.001)." (PMID 30597961, 2018). "The results confirmed that alterations involving RB1 and NFE2L2 were enriched in basal cancers, whereas alterations involving FGFR3 and KDM6A were enriched in luminal tumors." (PMID 29977169, 2018). "There were also associations unique to each cancer type, including USF1 and SMAD1 for BRCA, FOXF2 for HNSC, and NFE2L2 and NR3C1 for UCEC." (PMID 28139702, 2017). "Genetic alterations of KEAP1 or NFE2L2 (Nrf2 gene) in cancers, especially in lung cancers, are also uncovered by large-scale omic project." (PMID 27200299, 2016). "The decreased expression of NFE2L2 is characteristic of the paradoxical role of NFE2L2 in cancer progression." (PMID 27812189, 2016). "The Nrf2 (NFE2L2) cell defense pathway protects against oxidative stress and disorders including cancer and neurodegeneration." (PMID 26885667, 2016). "The role of NFE2L2 in cancer is subject of controversial discussion, as it has been reported to have both pro-and anti-tumourigenic functions." (PMID 27770790, 2016). "These showed increased expression in relation to NFE2L2 activating mutations primarily in bladder (BLCA), cervical (CESC), head and neck (HNSC) and LUSC carcinomas." (PMID 28959951, 2016). "Nuclear factor E2-related factor 2 (Nrf2 or NFE2L2) is abundantly expressed in cancer cells and relates to proliferation, invasion, and chemoresistance." (PMID 26194347, 2015). "We found that the number of KEGG cancer pathways of the NFE2L2-mediated genes is significantly larger than that of the random gene sets (P = 0.002)." (PMID 26596768, 2015). "We confirmed the critical role of NFE2L2 in carcinogenesis by the gene ontology analysis of all NFE2L2-mediated genes: 12 of 20 significantly deregulated pathways are direct cancer pathways." (PMID 26596768, 2015). "Gain-of-function mutations in NFE2L2 and inactivating KEAP1 mutations are the most frequent NRF2 activation mechanisms observed in breast, gallbladder, and lung tumors, among other cancer types." (PMID 25114896, 2014).
cancer (continued). "Consistent with a role for NFE2L2 in vitamin D-mediated cancer prevention, a number of NFE2L2 target genes were increased in RWPE1 cells after 1,25(OH)2D treatment, e.g. GPX3, HMOX1, AKR1C2, and TXNRD1." (PMID 20070897, 2010). "Genetic inactivation of KEAP1, or gain-of-function mutations in the NFE2L2 gene which encodes NRF2, produce highly malignant tumours which can evade the anti-cancer immune response, and are resistant to all existing anti-cancer therapies, including immune checkpoint inhibitors." (PMID 40890297, 2025). "Moreover, pan-cancer analyses have revealed recurrent co-mutations in KEAP1, NFE2L2, and NOTCH1, supporting a cooperative role in driving tumor progression." (PMID 40563292, 2025). "As a result, NFE2L2 has become a key target in cancer research, with ongoing efforts to develop activators for conditions requiring enhanced oxidative defense, such as neurodegenerative diseases, and inhibitors to counteract its role in tumor resistance and poor prognosis." (PMID 39534872, 2024). "In cancer, NFE2L2 exhibits a dual function depending on the disease context." (PMID 39534872, 2024). "It is reported that miRNAs that regulate VEGFA and NFE2L2 could serve as the therapeutic targets in various cancers." (PMID 38221932, 2024). "Overexpression of NFE2L2 is found to inhibit ferroptosis through eliminating ROS in cancer cells." (PMID 39248438, 2024). "Expanding research in this area is critical for optimizing ferroptosis modulation and may pave the way for innovative therapeutic strategies that utilize NFE2L2 inhibition to overcome drug resistance and improve clinical outcomes across various cancer types." (PMID 39534872, 2024). "These strategies, when employed in conjunction with existing treatments such as radiotherapy and targeted drug delivery systems, offer the potential for more comprehensive and durable cancer therapies by addressing both tumor survival mechanisms and NFE2L2-driven resistance pathways." (PMID 39534872, 2024). "So clinically we need to decrease the NFE2L2 level to promote the ROS level of cancer cells." (PMID 39877159, 2024). "This feedback mechanism might be expanded to 28 other types of human cancers because of a significant correlation between ZMYND8 and NFE2L2 mRNAs in these cancers." (PMID 38488001, 2024). "This multifaceted regulation of ferroptosis by NFE2L2 is believed to have been obtained during the evolution of multicellular organisms, allowing ferroptosis to be used to maintain homeostasis, including cancer suppression." (PMID 38685674, 2024). "In individuals with HCV-positive HCC, an NFE2L2 inhibitor may be able to reduce cancer cell resistance to anticancer medications." (PMID 39463763, 2024). "Understanding the delicate balance between NFE2L2’s protective and deleterious roles could pave the way for novel therapeutic strategies targeting NFE2L2 to enhance the efficacy of ferroptosis inducers in cancer therapy." (PMID 39534872, 2024). "Furthermore, miRNAs capable of regulating NFE2L2 were identified in the context of cancer and cardiovascular or neurodegenerative diseases." (PMID 37627486, 2023). "We have recently discussed that STAT3 may interact with NFE2L2, and their interaction may result in a synergic or antagonistic effect with respect to cancer cell survival." (PMID 37511362, 2023). "Previous studies, including our own, have shown that targeting NFE2L2 could be a promising strategy to reduce cell survival of several cancer types and to counteract chemoresistance when used in combination with other drugs." (PMID 37511362, 2023).